RTP5 (receptor transporter protein 5 (putative))
Synonyms: C2orf85; CXXC11; Z3CXXC5; FLJ33590
Tractability: Antibody: UniProt predicts a signal peptide or a membrane-spanning region. PROTAC: ubiquitination databases record sites on it.
Gene: Protein-coding gene on chromosome 2 (241,869,600 to 241,873,823, forward strand). Ensembl gene ENSG00000188011.
Subcellular location: Membrane
Gene Ontology:
Molecular function: protein binding; olfactory receptor binding
Biological process: detection of chemical stimulus involved in sensory perception of bitter taste; protein insertion into membrane; protein targeting to membrane
Cellular component: membrane
Genetic constraint (gnomAD): Loss-of-function variants: 30 observed, 22.22 expected, observed/expected ratio (o/e) 1.35, 90% interval 1.01 to 1.8. The upper end of that interval is the gene's LOEUF score, 1.8, which puts it in group 6 of 6, group 1 being the genes least tolerant of losing a copy. Missense variants: 807 observed, 721.53 expected, observed/expected ratio (o/e) 1.12, 90% interval 1.05 to 1.18. Synonymous variants: 354 observed, 304.69 expected, observed/expected ratio (o/e) 1.16, 90% interval 1.06 to 1.27.
Homologues: Orthologues: chimpanzee RTP5 (98% identical), macaque RTP5 (91% identical), dog RTP5 (39% identical), tropical clawed frog rtp3 (9% identical), tropical clawed frog rtp3d (7% identical), tropical clawed frog rtp3a.3 (6% identical). Paralogues in human: RTP3 (11% identical), RTP1 (10% identical), RTP2 (10% identical), RTP4 (10% identical).
Diseases named in the same sentence as RTP5 in open-access papers:
RTP5 is named in the same sentence as 1 disease in open-access papers, as found by Europe PMC text mining. Sharing a sentence is not in itself a finding about the gene and the disease.
RTP5 shares sentences with these, for which no sentence is quoted: Co-infection (1 paper).